FASN (fatty acid synthase)
Diseases named in the same sentence as FASN in open-access papers (continued):
Sharing a sentence is not in itself a finding about the gene and the disease.
liver fibrosis (11 papers, 2022 to 2026). "The effect of FASN inhibition was also evaluated in a therapeutic model of diet-induced NASH with CCl4 administration to cause liver fibrosis, recently termed the FAT (Fibrosis And Tumors)-NASH model." (PMID 36123383, 2022). "In parallel, PFD suppressed TGF-β-associated lipid accumulation in vitro, reduced SREBP1/FASN expression in activated HSC-rich regions in vivo, and alleviated CCl4-induced liver fibrosis." (PMID 42123641, 2026). "It has been reported in the liver that mitochondrial pyruvate carrier 1 (MPC1) regulates fatty acid synthase lactylation, affecting both liver fibrosis and nonalcoholic fatty liver." (PMID 38202819, 2024). "In agreement with this literature data reported up-regulation of FASN genes in several hepatic fibrosis animal models, and our results indicate an up-regulation of Cpt1a and FASN genes." (PMID 36579532, 2022). "FASN boosts aliphatic acid synthesis and is involved in various metabolic processes in hepatocytes, and its expression is positively correlated with the severity of hepatic fibrosis." (PMID 38813108, 2024). "Moreover, FASN dysfunction may trigger low-grade inflammation, which over time could contribute to liver fibrosis or cirrhosis, significantly changing the liver's appearance." (PMID 40339699, 2025). "Moreover, FASN expression was elevated in guinea pigs with liver fibrosis." (PMID 39125684, 2024). "TAK effectively alleviated ASD-induced disruptions in glycogen synthesis via PI3K/AKT/GSK3/GYS2 pathways, abnormal lipid accumulation via SREBP1/FASN/ACC, liver inflammation by balancing M1 and M2 macrophages, and liver fibrosis induced by ASD/CSD." (PMID 40331934, 2025). "We tested potent small molecule FASN inhibitors including TVB-2640 (denifanstat) in liver, immune and fibrogenic cells ex vivo, and in mouse models of NASH and liver fibrosis." (PMID 36123383, 2022). "The results suggested that FASN and FADS2 may function as pivotal players in the treatment of hepatic fibrosis by YYHXD." (PMID 38813108, 2024).
lung adenocarcinoma (11 papers, 2012 to 2024). A carcinoma that arises from the lung and is characterized by the presence of malignant glandular epithelial cells. "Several studies have revealed that FASN can be activated to enhance ERK2 or promote lipogenesis associated with lung adenocarcinoma and it is also expressed in the bronchial epithelium and epithelial hyperplasia in lung squamous cell cancer." (PMID 34879004, 2021). "CircFARSA, facilitated fatty acid synthesis and promoted lung adenocarcinoma progression via miR-330-5p/FASN axis." (PMID 38341418, 2024). "In KRAS signaling active lung adenocarcinomas, FASN is a primary responder that induces elevated lipogenesis which mediated by the ERK pathway." (PMID 35898882, 2022). "Similar with the results, high FASN expression was associated with poor OS, FP, and PPS in lung adenocarcinoma cases." (PMID 34879004, 2021). "FASN level is positively correlated to the malignant grades of tumor cells in both lung squamous cell carcinoma and lung adenocarcinoma." (PMID 34620841, 2021). "A former study showed that oncogenic KRAS induces fatty acid synthase (FASN) to enhance lipogenesis with a specific lipid signature in lung adenocarcinoma." (PMID 33194642, 2020). "In TCGA datasets, FASN expression was increased in both lung adenocarcinoma (n = 57, P < 0.001) and squamous carcinoma (n = 50, P = 0.005), compared with paired normal tissues." (PMID 29722168, 2018). "FASN expression was found to be associated with lung squamous cell carcinoma (Cox coefficient = 0.182, P = 0.0085), but not lung adenocarcinoma." (PMID 34879004, 2021). "FASN has been previously related to AKT/ERK/EGFR signaling pathways and the inhibition of the transcription factor STAT3 in lung adenocarcinomas." (PMID 32438613, 2020). "Overexpression of Fatty Acid Synthase (FASN) correlates with poor prognoses and treatment resistance in NSCLC, and stearoyl CoA desaturase 1 (SCD1) is highly expressed in lung adenocarcinomas promoting in vitro and in vivo tumorigenesis, cell migration and invasion." (PMID 36439419, 2022).
ovarian tumors (9 papers, 2010 to 2024). "Inhibitors of FASN have demonstrated efficacy as anticancer therapies based on the results of studies using cell lines and ovarian tumor mouse xenograft preclinical models." (PMID 35634242, 2022). "The overexpression of FASN has also been reported in different human tumors, such as adenocarcinoma of the prostate, ovarian neoplasm, and thyroid." (PMID 34573317, 2021). "The future study will examine the relationship between PTGIS and lipid metabolism molecules such as PPAR, FABP4, FASN, and CD36, as well as the effect of fatty acid metabolism on the growth and invasion of ovarian tumorous cells." (PMID 36785673, 2023). "For instance, fatty acid synthase (FASN) and stearoyl-CoA desaturase (SCD1) are elevated in high-grade, metastatic ovarian tumors and lead to elevated levels of unsaturated fatty acids." (PMID 35634242, 2022). "In our study, we have shown that while cisplatin on its own could not slow the growth of A2780cis ovarian tumours, inhibition of FASN with orlistat sensitised the cisplatin‐resistant tumours to cisplatin." (PMID 29569717, 2018).
Sepsis (9 papers, 2015 to 2025). Sepsis is defined as life-threatening organ dysfunction caused by a dysregulated host response to infection. "Fatty acid synthase upregulation by bNOS can cause activation of NLRP3 inflammasome during sepsis through the mitochondrial uncoupling protein-2 which is considered as a potential therapeutic target for inflammatory diseases." (PMID 26388860, 2015). "Also, inhibition of FASN has been reported to alleviate sepsis-associated inflammation via inhibiting the activation of inflammasome." (PMID 37414769, 2023). "The results showed that compared to healthy controls, the levels of FASN in plasma were significantly increased in patients with sepsis." (PMID 40369168, 2025). "Our work provides further support for the role of FASN as a central player in inflammation in more acute conditions, such as infections or sepsis." (PMID 29463677, 2018). "Consistently, PBMCs from sepsis patients exhibited increased mRNA expression of SREBF1, FASN, ACACA, and SCD1, supporting the clinical relevance of lipid biosynthesis activation." (PMID 40524162, 2025). "However, the role of FASN in sepsis-induced vascular dysfunction remains unclear." (PMID 40369168, 2025). "Previously, strategies to inhibit FASN and activate AMPK have been demonstrated to have beneficial effects in experimental models of sepsis and endotoxaemia." (PMID 32896106, 2020). "Using a model of sepsis, it was recently delineated that NLRP3 inflammasome activation itself is regulated by fatty acid synthase (Fasn)-dependent lipid synthesis." (PMID 30315247, 2018).
atherosclerosis (8 papers, 2014 to 2025). A disease characterized by the build-up of fatty material and calcium deposition in the arterial wall resulting in partial or complete occlusion of the arterial lumen. "Evidence suggests that reducing fatty acid synthase (FASN) in macrophages markedly decreases plaque formation in atherosclerosis models." (PMID 38667273, 2024). "The results of early atherosclerosis mice showed that GLSP was able to downregulate fatty acid synthesis-related genes (FASN, ACC1) and upregulate fatty acid catabolism-related genes (ATGL)." (PMID 36923537, 2023). "Furthermore, we demonstrate that FASN is essential for the transition of smooth muscle cells into foam cells, offering a potential therapeutic target for atherosclerosis." (PMID 38667273, 2024). "In the results of advanced atherosclerosis mice, GLSP was able to downregulate fatty acid synthesis-related genes (FASN, PPARγ, SCD1) and upregulate fatty acid catabolism-related genes (HSL)." (PMID 36923537, 2023). "Our results demonstrate that manipulating the key proteins that regulate cholesterol esterification and cholesterol efflux through the downregulation of FASN and KLF4 displays a trend that could increase cholesterol efflux and result in a slower progression of atherosclerosis." (PMID 38667273, 2024). "In contrast, our study reveals that elder extracts did not increase expression of SREBP1 and FASN in hepatic cells, indicating no safety concerns regarding the development of NAFLD if elder extracts are intended to be used to ameliorate atherosclerosis." (PMID 38347122, 2024).
cutaneous melanoma (8 papers, 2014 to 2025). A primary melanoma arising from atypical melanocytes in the skin. "The highest alteration frequency of FASN (>11%) was found in patients with Skin Cutaneous Melanoma with “mutation”." (PMID 34879004, 2021). "In contrast to most normal cells, fatty acid synthase is overexpressed in a variety of human cancers, including cutaneous melanoma, in which its elevated expression levels are associated with tumor invasion and poor prognosis." (PMID 28005927, 2016). "One such cancer is cutaneous melanoma, in which the level of FASN expression is associated with tumor invasion and poor prognosis." (PMID 24964211, 2014). "Immunohistochemical analysis with antibodies adipophilin, FASN, GLUT‐1, HIF‐1α, and Ki‐67 was performed in a series of 28 sinonasal melanomas (SM), 16 oral melanomas (OM), and 39 cutaneous melanomas (CM)." (PMID 40867038, 2025). "We also tested the effects of the FASN and mTOR inhibitors on a non-GNAQ mutant cutaneous melanoma cell line, A375." (PMID 37444561, 2023).
pulmonary fibrosis (8 papers, 2019 to 2025). Chronic progressive interstitial lung disorder characterized by the replacement of the lung tissue by connective tissue, leading to progressive dyspnea, respiratory failure, or right heart failure. "Loss of MFN1, MFN2 or inhibiting lipid synthesis via fatty acid synthase deficiency in AEC2 cells exacerbates bleomycin-induced lung fibrosis." (PMID 31358769, 2019). "Furthermore, overexpression of FASN considerably reduced lung fibrosis caused by collagen deposition, as shown by Masson’s trichrome staining and Ashcroft scoring." (PMID 37270622, 2023). "Moreover, the loss of AE2 cell-specific FASN results in a reduction of lipid synthesis and aggravates pulmonary fibrosis induced by bleomycin (BLM)." (PMID 36452229, 2022). "In summary, our findings indicate that FASN inhibition kept fibroblasts in a quiescent state and induced fibroblast lipogenic differentiation, which effectively alleviated pulmonary fibrosis." (PMID 39567194, 2025). "This study demonstrates that FASN expression is increased in fibroblasts from the lung tissues of patients with idiopathic pulmonary fibrosis and in bleomycin-treated mice." (PMID 39567194, 2025). "To address this issue, we examined the efficacy of FASN overexpression in the BLM-treated lung fibrosis model." (PMID 37270622, 2023). "They reported that FASN inhibition decreased BLM-induced lung fibrosis and that FASN was required for TGF-β1 signaling." (PMID 37270622, 2023). "The level of FASN is directly related to the degree of pulmonary fibrosis in a mouse model of pulmonary fibrosis." (PMID 36211517, 2022). "Consequently, targeting FASN inhibition in fibroblasts presents a promising therapeutic strategy for pulmonary fibrosis." (PMID 39567194, 2025). "Conversely, inhibiting FASN in fibroblasts may induce a quiescent state, potentially alleviating pulmonary fibrosis." (PMID 39567194, 2025). "In conclusion, these findings suggest that inhibiting FASN in fibroblasts may diminish the activity of the Wnt/β-catenin signaling pathway, providing a potential therapeutic avenue for pulmonary fibrosis." (PMID 39567194, 2025). "Next, we examined whether overexpression of FASN could prevent fibrotic activity in the BLM-induced lung fibrosis model." (PMID 37270622, 2023). "Overexpression of human FASN in AECs markedly attenuated BLM-induced lung fibrosis." (PMID 37270622, 2023). "The role of FASN during lipid metabolism in pulmonary fibrosis needs to be explored further." (PMID 36452229, 2022). "As demonstrated by Jung and colleagues, not only do FA synthase (FASN) levels directly correlate with the degree of fibrosis, but its inhibition reduces the expression of profibrotic genes and stabilizes or improves lung function in a bleomycin model of lung fibrosis." (PMID 41085570, 2025). "Our findings suggest that defects in FASN production may be associated with the pathogenesis of IPF, especially mitochondrial dysfunction, and augmentation of FASN in the lung may have therapeutic potential in preventing lung fibrosis." (PMID 37270622, 2023). "This study shows fatty acid synthase (FASN) inhibition induces quiescent fibroblasts, reduces β-catenin, and alleviates pulmonary fibrosis, suggesting FASN as a therapeutic target." (PMID 39567194, 2025). "After the inhibition of FASN expression, the degree of TGF-β-induced lung fibrosis is significantly reduced." (PMID 36211517, 2022).
intrahepatic cholangiocarcinoma (7 papers, 2020 to 2025). A carcinoma that arises from the intrahepatic bile duct epithelium in any site of the intrahepatic biliary tree. "circMBOAT2 was found in intrahepatic cholangiocarcinoma tissues and can facilitate FASN mRNA cytoplasmic export and altered lipid metabolic activity." (PMID 39402211, 2025). "Notably, FASN inhibitors markedly enhance the therapeutic effect of PD-1 monoclonal antibodies in patients with intrahepatic cholangiocarcinoma (ICC) associated with liver fluke infection, presenting a promising new treatment strategy for liver fluke-related ICC." (PMID 40161377, 2025). "Circular RNA (circRNA) circMBOAT2, located on chromosome 2p25, promotes lipid metabolic reprogramming in intrahepatic cholangiocarcinoma (ICC) through the circMBOAT2/PTBP1/FASN axis." (PMID 40392981, 2025). "However, whether mechanisms during intrahepatic cholangiocarcinoma (ICC) progression, such as circRNAs, regulate FASN expression remains unknown." (PMID 36635270, 2023).
metastatic tumors (7 papers, 2015 to 2025). "This association holds up when comparing benign and tumor cells, as well as comparing within primary or metastatic tumor cohorts, and remains significant when cases are stratified by molecular alterations associated with FASN expression, such as ERG gene fusions." (PMID 38112617, 2024). "In CM, the marked expression of FASN in metastatic tumors suggests that these proteins probably contribute to disease progression." (PMID 40867038, 2025). "In 8 (22.2%) of the paired cases, the primary tumor was FASN-positive, while the metastatic tumor was FASN-negative." (PMID 26334757, 2015). "Our results showed that FASN expression was significantly different between primary and metastatic tumors, and in most cases, the shift was from FASN-positivity in primary tumors to FASN-negativity in metastatic tumors." (PMID 26334757, 2015). "In metastatic tumors, fatty acid synthase is upregulated, and the expression of PPAR-α is highly amplified, which could upregulate the transcription of lipogenesis genes." (PMID 39859448, 2025). "However, significant upregulation of FASN occurs during prostatic tumorigenesis, with the highest levels expressed in metastatic disease." (PMID 38112617, 2024). "In addition to CD36, other proteins involved in FA uptake and synthesis, such as fatty acid synthase (FASN), are also frequently amplified and/or overexpressed in metastatic tumors." (PMID 37371076, 2023). "To further support the implication of Cav-1/ACC1/FASN signaling in the progression of PCa we performed Cav-1, ACC1 and FASN immunostaining in normal prostate tissues, primary untreated and ADT treated PCa and metastatic disease." (PMID 27331874, 2016).
neuroblastoma (7 papers, 2021 to 2025). Neuroblastoma (NB) is the most common solid, extracranial childhood tumor. "In neuroblastoma, expression of FASN is correlated with worse prognosis in patients and FASN inhibitors induced neural differentiation and decreased tumour burden in a xenograft animal model." (PMID 40621620, 2025). "Both bovine kidney (MDBK) and mouse neuroblastoma cells (Neuro-2A) were employed to investigate the effects of viral productive infection had on FASN protein expression in vitro." (PMID 41196069, 2025). "Similar to FASN, SCD has been strongly implicated in the development and progression of neoplastic disease including a neuroblastoma that is also vulnerable to treatment with polyamine pathway inhibitors." (PMID 39337514, 2024). "Our analysis showed that high levels of both ACACA and FASN correlate with reduced survival in three neuroblastoma patient cohorts covering all five INSS stages and with similar proportion of MYCN-amplification." (PMID 33659885, 2021). "Collectively, these data suggest that although high expression of both ACACA and FASN consistently correlates to reduced survival in tumors independently of their MYCN status, FASN seems to be a better prognosis marker candidate for neuroblastoma patients." (PMID 33659885, 2021). "We previously reported that MondoA knockdown in MYCN-driven neuroblastoma cells leads to induction of apoptosis due, at least in part, to decreased FASN (fatty acid synthase) expression and attenuated fatty acid biosynthesis." (PMID 34669700, 2021). "Notably high FASN expression is related to low levels of neural differentiation markers and to poor prognosis factors, suggesting that it may have a prognostic value in neuroblastoma." (PMID 33659885, 2021). "Using five small molecule inhibitors targeting ACACA or FASN and siRNA targeting FASN, we show that inhibition of fatty acid synthesis decreases cell proliferation, reduces MYCN or c-MYC protein levels, and results in neural differentiation in neuroblastoma." (PMID 33659885, 2021).